RNU6-592P (RNA, U6 small nuclear 592, pseudogene)
Gene: Small nuclear RNA gene on chromosome 11 (122,579,205 to 122,579,307, reverse strand). Ensembl gene ENSG00000223265.
Homologues: Orthologues: chimpanzee U6 (96% identical), mouse Gm23298 (92% identical), rabbit U6 (92% identical), macaque U6 (80% identical). Paralogues in human: RNU6-1011P (92% identical), RNU6-1060P (91% identical), RNU6-12P (91% identical), RNU6-13P (91% identical), RNU6-15P (91% identical), RNU6-32P (91% identical), RNU6-33P (91% identical), RNU6-41P (91% identical), RNU6-1 (90% identical), RNU6-1020P (90% identical), RNU6-1122P (90% identical), RNU6-116P (90% identical), and 1287 more.